LEP (leptin)
Diseases named in the same sentence as LEP in open-access papers (continued):
Sharing a sentence is not in itself a finding about the gene and the disease.
cancer (continued). "The OB3 peptide, a synthetic peptide, was shown to be more active than leptin in regulating metabolism but with no mitogenic effects in cancer cells." (PMID 28750624, 2017). "The growth inhibition of adiponectin in cancer cells was shown to be mediated through activation of AMPK, inhibition of PI3K/Akt and ERK1/2 pathways, down-regulation of leptin-induced STAT3 phosphorylation, inhibition of NF-κB and Wnt/β-catenin pathways, and decrease of ROS production." (PMID 28915700, 2017). "CAFs could also respond to leptin to increase TGFB1 for paracrine signalling thus targeting TGFB1 and leptin signalling could target both cancer cell and CAF contributions to these synergistic metastatic pathways in tumors." (PMID 28542577, 2017). "Median leptin levels were 12.9 (interquartile range [IQR] 5.8–29.5) ng/ml in the incident cancer group vs. 12.3 (IQR 5.4–26.4) ng/ml those without an incident cancer (p = 0.34)." (PMID 27636369, 2016). "Moreover, leptin and miR-4443 transfection significantly down-regulated endogenous NCOA1 and TRAF4, both predicted targets of miR-4443 with known roles in cancer metastasis." (PMID 27842582, 2016). "Participants enrolled in the DHS without prevalent cancer and with baseline leptin measurements were included." (PMID 27636369, 2016). "This may signify differential roles between leptin and CRP in the scope of cancer, which require further biological investigations." (PMID 26632325, 2016). "Interaction between CRP and leptin is likely to be minimal in the study on cancer mortality, unlike previous evidence suggested in cardiovascular disease." (PMID 26632325, 2016). "Additionally, increased body weight as well as increased leptin and IGF1 signaling are positively correlated with GI pathologies including inflammatory bowel disease and cancer." (PMID 27558773, 2016). "Leptin has been shown to induce VEGF and FGF in different cancer cell types in vitro." (PMID 27050378, 2016). "We found a lack of association between leptin and cancer death, whereas CRP was positively associated to cancer death in men." (PMID 26632325, 2016). "Because circulating leptin levels do not necessarily reflect the ascites leptin levels, we also measured leptin levels in ascites samples collected from overweight and healthy BMI cancer patients." (PMID 26053184, 2015). "While autophagy induction correlates to the survival of cancer cells, the relationship if any between leptin-induced tumor growth and autophagy activation has not been explored." (PMID 25704884, 2015). "Because the classic effects of leptin are stimulating α-MSH neurons and inhibiting NPY neurons, decreasing food intake, and increasing energy expenditure, a leptin-independent pathway of cancer cachexia has been proposed." (PMID 26508818, 2015). "In fact, leptin's effects on cell migration and invasion were observed in both low-OB-Rb-expressing (e.g., SKOV3) and in middle- or high-expressing (e.g., HEY and Asc3 primary tissue culture) cancer cells using wound-healing and Boyden chamber assays." (PMID 26053184, 2015). "Interestingly, it has been found that leptin induces the expression of CD44 and ALDH1 in several cancer cell lines." (PMID 25505738, 2014). "On the other hand, because leptin promotes autoimmunity, cancer cell growth and migration, the identification of new OBR antagonists would be of interest in the field of autoimmune disease and cancer therapy." (PMID 25352831, 2014). "Animal and clinical studies have also demonstrated that leptin levels are not elevated in tumor-bearing rats and patients with cancer cachexia." (PMID 24624094, 2014). "The two best performing molecules that can distinguish RM from cancer are CA125 (AUC = 0.752) and CRP (AUC = 0.708), while the best molecules which can separate RM and HC are PDGF-AB/BB, PDGF-AA, sIL6R and Leptin (AUC = 0.815, 0.731, 0.739 and 0.73, respectively)." (PMID 24244307, 2013).
cancer (continued). "Importantly, most of these identified genes, such as FLT1, EBI3, LEP and BCL6, are highly involved in angiogenesis and immune modulation in malignant tumor progression." (PMID 22929622, 2012). "Proangiogenic effects of leptin can be further potentiated by its ability to upregulate the expression of other angiogenic factors, such as VEGF, bFGF, interleukin 1-β, and leukemia inhibitory factor in cancer cells." (PMID 21771332, 2011). "Moreover, according to our knowledge, there are no published data regarding the role of PRAT-derived leptin in other types of cancers, necessitating supplementary studies in the near future." (PMID 40227577, 2025). "In addition, Leptin has been shown to upregulate the expression of IL-8 in M2 macrophages and IL-18 in TAMs, increase the expression of PLOD2, and promote the metastasis of cancer cells." (PMID 39192979, 2024). "Moreover, altered adipokine secretion, characterized by increased leptin and decreased adiponectin levels due to adiposity in T2DM, may facilitate cancer progression through pro-inflammatory and anti-apoptotic effects." (PMID 38731833, 2024). "In addition, leptin and adipocyte-derived IL-6 enhance the expression of lysyl hydroxylase (PLOD2) by activating the JAK/STAT3 and PI3K/AKT signaling pathways, ultimately facilitating cancer cell metastasis." (PMID 39192979, 2024). "Several studies describe that leptin promotes the expression of mesenchymal markers and decreases epithelial markers, in addition to promoting EMT-related processes such as cell migration and invasion and a poor prognosis in patients with numerous types of cancer." (PMID 37686525, 2023). "Moreover, the crosstalk between leptin with NOTCH, IL-6 receptor, and other different growth factor receptors (VEGFR, IGFR and EGFR) has been well documented to promote the development and progression of several cancer cells." (PMID 37509120, 2023). "However, this rescue of STAT3 phosphorylation by insulin, IGF1 and leptin was no longer detectable when the cancer cells were treated with the cholesterol-depleting agent MβCD." (PMID 37907500, 2023). "Inhibition of apoptosis, angiogenesis, and promotion of cancer cell proliferation and migration may involve high levels of leptin, while low levels of adiponectin may interrupt the AMP-activated protein kinase (AMPK) and the insulin-signal pathways, which lead to cancer cell proliferation." (PMID 36555323, 2022). "Interestingly, additional experiments clearly showed that leptin-induced angiogenesis was probably attributed to activating VEGFR-Notch signalling crosstalk in overweight cancer patients with increased expression of VEGF, VEGFR-2, and Notch." (PMID 36578551, 2022). "Interestingly, IL-6 together with leptin can increase the expression of procollagen-lysin-2-oxoglutarate 5 dioxygenase (PLOD2), a protein involved in ECM remodeling, and therefore has a decisive role in cancer cell invasion and EMT." (PMID 35625629, 2022). "Despite the potential ERα-dependent effect of APN, patients with low leptin/APN ratios have shown a statistically longer cancer-specific survival for OC, which may show APN as a good candidate against DIO and derived metabolic diseases, including cancer." (PMID 35681689, 2022). "Indeed, upon binding its receptor (LEPR), leptin activates several oncogenic pathways, such as JAK/STAT, MAPK, and PI3K/AKT, and seems to affect cancer immune response by inducing a proinflammatory immune polarization and eventually enhancing T-cell exhaustion." (PMID 36291602, 2022). "In addition, results revealed that body weight did not influence serum leptin and ObR levels, both in the control group (p = 0.0760 and p= 0.8432, respectively) and in the cancer group (p = 0.3294 and p = 0.9722, respectively)." (PMID 33644151, 2021).
cancer (continued). "The upregulation of heat shock protein 27 (hsp27) in leptin treated MCF-7 cells may also account for the leptin-induced metastasis, since the role of hsp27 is well documented in suppressing apoptosis and promoting cancer cell invasion and metastasis." (PMID 34588926, 2021). "However, leptin does not affect metastatic spread so its prognostic effect in cancer is not so consistent." (PMID 34205356, 2021). "Furthermore, leptin was reported to elicit chemoresistance in pancreatic ductal adenocarcinoma, and the results indicated that gemcitabine resistance develops via miR-342-3p upregulation-dependent inhibition of KLF6 signaling in cancer cells." (PMID 33799880, 2021). "Hence, it could be reasoned that modulatory effects of leptin on SREBP is determined by context‐dependent manners and SREBPs induction by leptin would be specific for cancer cells, which may play a key role in its tumor‐promoting effects." (PMID 33226729, 2021). "Despite the well-established role of leptin in promoting tumour growth, no pharmacological interventions directly targeting leptin signalling are currently approved for the prevention or treatment of cancer." (PMID 33911195, 2021). "Using RT-PCR to examine expression levels of genes in circulating leukocytes, it was shown that TNF-alpha, IL-6, leptin and ErbB2, were significantly higher in obese individuals without a cancer diagnosis and among breast cancer patients compared to the lean group." (PMID 33597950, 2020). "Although leptin stimulates PAI-1 expression by activating the ERK1/2 pathway in human vascular endothelial cells, the detailed molecular mechanisms behind this regulation remain unclear in cancer cells." (PMID 33371368, 2020). "Leptin increases the expression of anti-apoptotic proteins, inflammatory markers (tumor necrosis factor, TNF-α, interleukin IL-6) and angiogenic factors (vascular endothelial growth factor, VEGF), all processes involved in cancer cell survival, proliferation and migration." (PMID 32854444, 2020). "Furthermore, by screening through the criteria of the PPI network, cancer-related pathway and TRS modeling, essential features with gene symbols of EPB41, PSMA1, FGFR3, MRAS, LEP, C7orf46, LOC285000, LBP, ZNF35, SLC30A3, LECT2, RNF7, and DYNC1I1 were identified as PRBs for COAD patients." (PMID 32528533, 2020). "Cancer cells treatment with leptin induces the secretion of both intracellular adhesion molecule 1 (ICAM-1) and RANKL and enhances tumor-induced osteolysis in vivo, suggesting a potential role for leptin in osteoclast-like giant cell formation in a cancer context." (PMID 33203195, 2020). "Nevertheless, unlike healthy controls and cancer patients not suffering weight loss, IL-6 plasma levels were strongly elevated, which fits the observation that ZAG expression is stimulated by hormones such as IL-8, leptin and IL-6." (PMID 32315567, 2020). "In addition, the crosstalk between leptin and epidermal growth factor receptor (EGFR) signaling pathways could alter significantly the behavior of different cell types in cancer." (PMID 31380268, 2019). "Also, JAK2 phosphorylates STAT3 at Tyr705, inducing its dimerization and translocation to the nucleus where it regulates the expression of different proteins involved in cancer progression, such as cyclin D1, COX2, VEGF, and SOCS3, a negative regulator of leptin signaling." (PMID 30404206, 2018). "It is noted that the relative expression levels of leptin and leptin receptor were not uniformly distributed in the pan-cancer cohort, which provides a basis for the pathological involvement of other leptin receptors in tumors, which requires further exploration." (PMID 29682217, 2018). "Moreover, leptin has been shown to induce the expression of various MMPs, such as, MMP-2, MMP-9, and membrane type 1 matrix metalloproteinase (MT1-MMP/MMP-14) in human cancer cells." (PMID 30510663, 2018).
cancer (continued). "The data demonstrated that leptin and LepRb protein levels were significantly increased (2.8-fold and 2.3-fold higher) in depressive GC patients (n = 16) compared with the nondepressive cancer patients (n = 16)." (PMID 28316984, 2017). "Moreover, we analyzed whether leptin-induced proliferative responses in 1321N1 cells involved EGFR or PDGFR, important signaling mechanisms in cancer cells." (PMID 28249041, 2017). "Interestingly, recent studies have also reported that leptin signaling may be involved in the promotion of CSC phenotype and that inhibition of STAT3 suppresses leptin-induced CSC activity and cancer progression in diet-induced obese rats." (PMID 26556856, 2016). "Our findings therefore indicate that the associations between leptin or CRP and cancer may be unique and do not resemble the additive effects observed with cardiovascular disease." (PMID 26632325, 2016). "However, we observed different effects between leptin and CRP levels on cancer mortality." (PMID 26632325, 2016). "However, the effects of leptin on autophagy induction and its potential roles in cancer development have not been explored." (PMID 25704884, 2015). "In addition, the effect of leptin on autophagy induction in different types of cancer cells and its role in leptin-induced various biological responses have not been explored." (PMID 25704884, 2015). "It should be noted that these publically available resources do not separate the tumor stroma from the cancer cells, and as such increased leptin expression could correlate with increased expression of leptin in the tumor stroma, where the ASCs are localized." (PMID 24176089, 2013). "Leptin signaling plays an important role in tumor cell growth and survival that may be mediated through a set of responses of LEPR-positive tumor cells including cancer stem cells." (PMID 23819063, 2013). "This dysregulation of the normal feedback loop in cancer cachexia may explain why a decrease in leptin does not increase appetite or lower energy expenditure in patients with cancer cachexia." (PMID 22518191, 2012). "However, the exact mechanism by which leptin exerts proliferative effects on cancer cells, including those from the prostate, is not fully understood." (PMID 22690216, 2012). "This crosstalk could explain why, despite low levels of leptin in chronic inflammatory processes such as cancer, COPD, and aging, patients do not have the expected increased appetite or lower energy expenditure." (PMID 22518191, 2012). "Both leptin and Ob-R are over-expressed in cancer tissue relative to non-cancer epithelium." (PMID 21139583, 2011). "Whilst the literature may be consistent in reporting that leptin is found in higher concentrations in those patients with EC versus non-cancer controls, this does not appear to be independent of BMI after all, suggesting that leptin may not be a useful standalone diagnostic biomarker." (PMID 40902078, 2025). "However, leptin treatments have not yet been fully applied in cancer because the mechanisms that involve leptin in those malignancies remain unknown, especially since the dual role of leptin in carcinogenesis has been suggested." (PMID 34202969, 2021). "Reports show that both leptin (LEP) and growth hormone 1 (GH1) could activate Janus kinase (JAK)–signal transducer and activator of transcription (STAT) cascade, which further induces angiogenesis, proliferation, and antiapoptotic pathways in normal cells and favors cancer progression." (PMID 32984004, 2020). "Therefore, the use of non-toxic leptin antagonists that interferes with leptin signaling could serve as a novel mechanism to target leptin-induced cancers." (PMID 33511131, 2020). "Mitochondrial dysfunction following 24 hours treatment with leptin may be a consequence of initial increase in fatty-acid oxidation due to higher fatty-acids concentrations and AMP activated protein kinase activation, in order to support increased-ATP demand of cancer cells." (PMID 24073224, 2013).
cancer (continued). "The safety and efficacy of leptin therapy in patients with ICI-induced AGL and cancer are therefore not clear." (PMID 41700130, 2026). "However, leptin might not seem to play a significant role in the development of cancer cachexia." (PMID 38534454, 2024). "Since LEP/LEPR is over-expressed in so many processes, they could not be generally used as cancer markers; however, if specific phenotypic variants of LEPR are involved with cancers, which is yet to be studied, then such phenotypes could be used as cancer markers." (PMID 31592340, 2019). "However, leptin may not be involved in cancer cachexia development." (PMID 28160559, 2017). "However, the leptin may not appear to play an important role in cancer cachexia development." (PMID 28160559, 2017). "Nevertheless, we did not observe any alteration in our findings after leptin and CRP were both included in the same analysis, thus suggesting minimal interaction between serum leptin and CRP with respect to cancer mortality as an outcome." (PMID 26632325, 2016). "The analyses show that the concentration of leptin did not correlate statistically significantly with the degree of histological differentiation, lymph node metastases, the stage of TNM, tumor size, the occurrence of cancer in the family, or lifestyle." (PMID 36981858, 2023). "Moreover, although previous studies have described the relationship between cathepsins and leptin, CTSA has not been extensively studied in cancer metastasis." (PMID 33255835, 2020). "However, inconsistently with previous studies in cancer cells, we did not observe the downregulation of STAT3 acetylation after STAT3-HDAC3 complex formation in human primary chondrocytes in response to leptin." (PMID 26636769, 2015). "The lack of difference in leptin levels between premenopausal and postmenopausal women in the WDTC group might have been masked by the presence of the cancer as documented earlier." (PMID 24867470, 2014). "Notably, these cancer biomarkers functionally comprised of several cytokines (IL-6, MIF, TGF-α, TNFα), apoptosis-related proteins (sFas, sFasL, TRAIL), growth and angiogenic factors (FGF2, HGF, SCF, VEGF), hormones (leptin, prolactin) and other biomarkers (AFP, OPN), but not carcinoma antigens." (PMID 31089160, 2019).